PRADX (PRC2 and DDX5 associated lncRNA)
Gene: Long non-coding RNA gene on chromosome 11 (1,760,348 to 1,762,486, forward strand). Ensembl gene ENSG00000235027.
Diseases named in the same sentence as PRADX in open-access papers:
PRADX is named in the same sentence as 7 diseases in open-access papers, as found by Europe PMC text mining. Sharing a sentence is not in itself a finding about the gene and the disease. The quoted sentences say what the papers report.
glioblastoma (6 papers, 2021 to 2025). The most malignant astrocytic tumor (WHO grade IV). "Compared to LacZ probes (non-targeting control), both even and odd probe sets pulled down most of the PRADX from U87-MG human glioblastoma cells." (PMID 33754075, 2021). "Further, we identified and characterized a novel lncRNA, ENST00000449248.1 (PRADX) that was found to be upregulated in glioblastoma (GBM) and colon adenocarcinoma (COAD), and predominantly localized in the nucleus of tumor cells." (PMID 33754075, 2021). "PRADX recruits the PRC2/DDX5 complex to promote glioblastoma and colon cancer." (PMID 35992805, 2022). "For example, lncRNA PRADX activates the NF‐κB pathway by inhibiting UBXN1 expression, thereby promoting the occurrence of glioblastoma and colon adenocarcinoma." (PMID 40095756, 2025). "YTHDF2 and PRADX decrease UBXN1 expression at the posttranscriptional level and thereby facilitate NF-κB signaling activity in glioblastoma and colon adenocarcinoma progression." (PMID 38773518, 2024).
colon adenocarcinoma (4 papers, 2021 to 2025). "We confirmed that PRADX could serve as a potential prognostic indicator of GBM and colon adenocarcinoma (COAD)." (PMID 35574370, 2022).
colon cancer (2 papers, 2022 to 2025). "In addition, studies report that PRC2 and DDX5-related lncRNA (PRADX) are highly expressed in colon cancer." (PMID 40535805, 2025).
glioma (1 paper, 2021). A benign or malignant brain and spinal cord tumor that arises from glial cells (astrocytes, oligodendrocytes, ependymal cells). "Additionally, ISH assays using 20 low grade glioma tissues, 22 GBM tissues, and 30 COAD and adjacent normal tissues further confirmed the predominant nuclear distribution of PRADX in tumor cells, and indicated its high expression in GBM and COAD." (PMID 33754075, 2021).
tumor (3 papers, 2021 to 2025). "Western blot analysis showed that tumor cells overexpressing PRADX had reduced levels of BLCAP and increased nuclear levels of phosphor(p)-STAT3." (PMID 35574370, 2022). "Western blot analysis showed that tumor cells overexpressing PRADX had reduced levels of UBXN1, which in turn decreased IκBα levels and increased the nuclear levels of NF-κB and p-NF-κB." (PMID 33754075, 2021). "In xenograft models, PRADX knockdown suppressed tumor growth and tumorigenesis and prolonged the survival of tumor-bearing mice." (PMID 33754075, 2021). "Activated NF-κB pathway, which is well-known as a dominant character of the inflammation and tumorigenesis of GBM and COAD 52-54, contributes to PRADX mediated tumor progression." (PMID 33754075, 2021). "Furthermore, colony formation assays also demonstrated the inhibitory effects of Triacsin C (30uM), and Etomoxir (30uM) on tumor cell growth in PRADX overexpressed N33 and N9 cells." (PMID 35574370, 2022). "However, treatments with Triacsin C (30μM) and Etomoxir (30μM) alone or in combination significantly inhibited cell viability in PRADX overexpressed tumor cells." (PMID 35574370, 2022). "PRADX, mainly located in the nucleus of tumor cells, could bind to EZH2 protein via the 5' terminal sequence." (PMID 33754075, 2021). "Inhibition of PRADX could suppress tumor growth and tumorigenesis, and prolong the survival of tumor bearing mice, indicating that PRADX acts as a cancer driver, and may serve as a potential therapeutic target." (PMID 33754075, 2021). "Knockdown of PRADX significantly inhibited tumor cell viability and clonogenic growth in vitro." (PMID 33754075, 2021). "Finally, we determined that combined of ACSL1 and CPT1 inhibitors could reverse the accelerated cellular metabolism and tumor growth induced by PRADX overexpression in vivo and in vitro." (PMID 35574370, 2022). "PRADX overexpression suppressed BLCAP expression via recruitment of H3K27me3, activating the phosphorylation of BLCAP interacting protein STAT3 and accelerating tumor metabolism and ATP production, resulting in tumor proliferation and poor survival outcomes." (PMID 35574370, 2022). "Moreover, we showed that BLCAP interacted with STAT3 and reduced STAT3 phosphorylation, overexpressed PRADX activated STAT3 phosphorylation, and promoted ACSL1 expression via suppressing BLCAP expression, accelerating tumor metabolism." (PMID 35574370, 2022). "However, EZH2 knockdown with or without PRADX overexpression in tumor cells revealed increased levels of BLCAP and reduced nuclear levels of p-STAT3." (PMID 35574370, 2022).
cancer (1 paper, 2021). A tumor composed of atypical neoplastic, often pleomorphic cells that invade other tissues. "We identified a novel cancer driver lncRNA, PRADX that recruits PRC2/DDX5 complex by interacting with EZH2 and promotes NF-κB activity via UBXN1 suppression, which in turn contributes to GBM and COAD tumorigenesis." (PMID 33754075, 2021). "Furthermore, clonogenic assays demonstrated that PRADX knockdown significantly inhibited the growth of cancer cells compared to siRNA control." (PMID 33754075, 2021).
PRADX also shares sentences with these, for which no sentence is quoted: hepatocellular carcinoma (1 paper).